IL1R1 (interleukin 1 receptor type 1)
Diseases named in the same sentence as IL1R1 in open-access papers (continued):
Sharing a sentence is not in itself a finding about the gene and the disease.
cancer (continued). "Here, we show that ligand-activated GPER triggers the EGFR/ERK/PKC signal transduction pathway generating a feedforward loop that couples IL1β induction by CAFs to IL1R1 expression by cancer cells." (PMID 27072893, 2016). "We found that TGFβ reduced the expression of IL-1R1 on PSCs which subsequently diminished their ability to stimulate cancer cell migration upon IL-1α stimulation." (PMID 27473228, 2016). "Immunohistochemistry of intact PDAC tissue showed expression of IL-1R1 in both stroma cells and cancer cells." (PMID 27473228, 2016). "Silencing of endogenous SMAD7 reduced PSC expression of IL-1R1 and attenuated the effects exerted by IL-1α on the ability of PSCs to stimulate cancer cell migration." (PMID 27473228, 2016). "We next examined the possible involvement of TGFβ from the cancer cells in the observed PDAC cell-induced down-regulation of IL-1R1 expression in PSCs." (PMID 27473228, 2016). "Silencing of stellate cell expression of SMAD7 was found to suppress the levels of IL-1R1 and reduce the stimulatory effects of IL-1α, thus inhibiting the capacity of pancreatic stellate cells to induce cancer cell migration." (PMID 27473228, 2016). "Depletion of SMAD7 upregulated the effects of TGFβ and reduced the expression of IL-1R1, leading to inhibition of IL-1α induced stellate cell enhancement of carcinoma cell migration." (PMID 27473228, 2016). "IL‐1β could directly bind to IL‐1R‐1 expressed in HLECs and promoted the tube formation capacities, which suggests a novel mechanism of cancer‐related lymphangiogenesis in OSCC." (PMID 40135589, 2025). "Signaling through IL-1R1 on stromal and immune cells stimulates the production of factors that recruit myeloid-derived suppressor cells (MDSCs), which potently suppress the activity of cancer-killing T cells and Natural Killer (NK) cells." (PMID 41415279, 2025). "In conclusion, SOAT1 could promote OSCC malignancy and regulate the activation of NLRP3 inflammasome to increase the rate of lymphangiogenesis and cancer metastasis via IL‐1β/IL‐1R‐1 axis in OSCC." (PMID 40135589, 2025). "To broaden the scope of our study of the IL-1α/IL-1R1 axis of age-enhanced emergency myelopoiesis, we wanted to determine whether this proposed mechanism for aging-driven cancer progression is relevant to other cancer settings." (PMID 39236155, 2024). "IL1R1 expression predicts poor survival in nearly the same set of cancer types as IL6R." (PMID 37006265, 2023). "Indeed, KRAS-mutant mouse and human cancer cell lines displayed markedly increased baseline Il1r1/IL1R1 mRNA expression compared with WT cell lines, and significantly downregulated Il1r1/IL1R1 transcript levels after deltarasin treatment." (PMID 35327394, 2022). "IL-1R1 is located on the membrane surface, thus, icIL-1RA would require secretion into the extracellular space for it to block IL-1R1, although IL-1R1 intranuclear localization in oral dysplastic and cancer cells has been recently described." (PMID 35048046, 2021). "IL-1R1 antagonist (IL-1Ra) completely abolish IL-1β-induced enhancement of nociceptive neuron responses and produce anti-allodynic effects in rat model of neuropathic, inflammatory, and cancer pain." (PMID 28645297, 2017). "Furthermore, depletion of SMAD7 upregulated the effects of TGFβ and reduced the expression of IL-1R1, leading to reduced stellate cell enhancement of carcinoma cell migration." (PMID 27473228, 2016). "We found that compared to CTNNB1 WT carcinomas, samples harboring CTNNB1 mutations showed significantly decreased levels of IL1A (p-value = 0.045), IL1B (p-value = 0.12), and caspase 1 (p-value = 0.037), while demonstrating similar IL1R1 and IL1R2 expression levels." (PMID 41227323, 2025). "Thus, the ligand-activated GPER triggers the Epidermal Growth Factor Receptor (EGFR)/extracellular signal–regulated kinases(ERK)/PKC signaling transduction pathway generating a feed forward loop that couples IL-1β induction by CAF to IL-1R1 expression by cancer cells." (PMID 30042333, 2018).
cancer (continued). "The interaction of IL-1β with its IL-1 Type 1 receptor (IL-1R1) activates β-catenin-dependent signaling, upregulating TWIST1 and SNAIL1 and triggering the EMT program in cancer cells." (PMID 39201656, 2024). "Within this set of genes, a subset, notably CSF2RA, CRLF2, IL1R1, IL7R, and PDGFRB, exhibited intricate connections with the JAK-STAT pathway, which is crucial for the viability of cancer cells." (PMID 38743676, 2024). "The anti-cancer response following APC-T cell interaction involves the APC-secreted IL-1, which activates IL1R1 signaling in CD4+ T cells and promotes production of many effector cytokines." (PMID 37563620, 2023). "In summary, we showed that KRAS-mutant cancer cells express CCL2 and IL1R1 to initiate an inflammatory signaling loop with CCR2/IL-1β-expressing myeloid cells." (PMID 35327394, 2022). "In cancer colonocytes, the activation of pro-inflammatory genes was not so evident compared to the healthy ones, but elevated levels of TLR4, IL1R1 and TNFα in some bacteria- and bacteria with hPA120-treated HCT116 cells were found." (PMID 36296918, 2022). "We found that seven genes (ADPRH, IL1R1, KSR1, SOCS2, JAK1, NFAT5, and SSH1) were more highly expressed in the lower-TMB subtype than in the higher-TMB subtype of more than 10 cancer types." (PMID 30634925, 2019). "Normal B and cancer 1 clusters shared inflammatory markers CCL2, TNFRSF12A, and IL1R1, pathways including TNFα, IL, and Myc signaling, and activity of inflammation, hypoxia, and lipid metabolism–associated transcription factors NFATC2, ARNT, PPARA, and PPARGC1A." (PMID 40215177, 2025). "Thereafter, we provide novel mechanistic evidence on the hypoxia-prompted liaison between the HIF-1α/GPER signaling and the IL-1β/IL1R1 axis, toward a metastatic gene expression profile of TNBC cells and the engagement of CAFs in facilitating invasive cancer features." (PMID 32778144, 2020). "Notably, TNFAIP8L3, CCL14, CX3CR1, CCL21, IL1R1, and IL33 had higher expression levels in the lower-TMB subtype of at least 13 cancer types, while had higher expression levels in the higher-TMB subtype of at most 2 cancer types." (PMID 30634925, 2019). "An absence of E-cadherin promotor methylation in IL-1R1-/- mice was observed, therefore IL-1 induced methylation is likely to be one of the major mechanisms for chronic inflammation inducing cancer." (PMID 30042333, 2018). "Taken together these data suggest that IL-1β and IL-1R1 promote cancer growth and metastasis by up-regulating CXCR4 expression and that CXCR4 may be a link between inflammation and cancer." (PMID 26176534, 2015). "The inhibitory effects of IL1β and the positive correlation of IL1R1 levels with AR activities in LNCaP, but not C4-2 cells, suggested an interplay between the inflammation and androgen signals in maintaining the homeostasis of androgen-sensitive prostate tissues and cancers." (PMID 33322099, 2020).
inflammation (17 papers, 2011 to 2025). Aberrant reaction of the microcirculation characterized by movement of fluid and leukocytes from the blood into extravascular tissues. "To determine specifically the contribution of IL-1R1 signaling to airway inflammation, we induced airway inflammation in Il1r1-/- mice." (PMID 26978520, 2016). "Il1r1−/− mice were protected from ozone-mediated airway inflammation, demonstrating that IL-1 pathway is necessary for IL-17A+ γδT-cells and neutrophilic airway inflammation." (PMID 26739627, 2016). "This study demonstrated that FD, attenuates BLM‐induced pulmonary inflammation and fibrosis in mice via inhibiting the activation of NALP3 inflammasome and the IL‐1β/IL‐1R1/MyD88/ NF‐κB pathway." (PMID 27306439, 2016). "In conclusion, FD attenuates BLM‐induced pulmonary inflammation and fibrosis through suppressing the activation of NALP3 inflammasome and the IL‐1β/IL‐1R1/MyD88/NF‐κB signalling pathway." (PMID 27306439, 2016). "IL-13, IL-1R1, IL-18, and BRP-39 knock out (KO) mice were utilized to assess the mechanism and relevance of BRP-39 in cigarette smoke- and HDM-induced airway inflammation." (PMID 21473774, 2011). "In vivo, treatment of Aspergillus-infected Il1r1–/– mice with anakinra increased the ratio of LC3-II/I and decreased p62, a ubiquitin-binding protein that is selectively degraded by autophagy; inhibited IL-6, IL-17A, IL-1β, and IL-1α production; increased IL-10; and ameliorated lung inflammation." (PMID 34847078, 2022).
bacterial infection (11 papers, 2011 to 2025). "Our findings that MyD88 and IL-1R mediate antibacterial protection in bone are consistent with data from previous studies demonstrating that Myd88-/- and Il1r1-/- mice have enhanced susceptibility to bacterial infection in various experimental models." (PMID 30978245, 2019).
kidney disease (6 papers, 2015 to 2025). "Our study highlights the cell-type specific effects of IL-1R1 that may offer further insights into targeting IL-1/IL-1R1 in kidney disease." (PMID 38693918, 2024). "We found here that the activation of IL-1R1 in human mesangail cells induced a transient but robust up-regulation of CXCL1, 2, and 8, suggesting that IL-1 gene cluster may involve in the pathogenesis of renal diseases by induction of CXC chemokines." (PMID 26648169, 2015).
neurodegenerative disease (5 papers, 2013 to 2025). A disorder of the central nervous system characterized by gradual and progressive loss of neural tissue and neurologic function. "Although neuron expresses higher level of IL-1R1 compared with microglia, IL-1R1 on both cells were involved in the neuroinflammation and neurodegenerative diseases." (PMID 38438808, 2024). "This implies that astrocytic IL-1R1 may contribute to degeneration in a variety of neurodegenerative diseases and CNS injuries." (PMID 36184639, 2022).
cardiovascular disease (4 papers, 2015 to 2021). "The Interleukin-1 receptor type 1, IL-1RT1, was associated with the risk of developing cardiovascular disease." (PMID 33536059, 2021).
kidney (4 papers, 2017 to 2025). "Following IR injury, Pepck-Cre+ Il1r1fl/fl mice (with proximal tubule–specific deletion of Il1r1) with or without LIPUS presented significantly milder kidney atrophy, tubular injury, and tubulointerstitial fibrosis compared with male Pepck-Cre– Il1r1fl/fl littermates (controls)." (PMID 40729113, 2025).
central nervous system diseases (3 papers, 2022 to 2024). "Many researchers are interested in the function of endothelial IL-1R1 in central nervous system diseases." (PMID 38087170, 2024). "Taken together, these studies suggest that the downregulation of the IL-1R1/IL-1β signaling pathway by RNA interference may be neuroprotective in CNS disorders." (PMID 35163653, 2022).
metabolic disease (3 papers, 2013 to 2025). A congenital disorder (due to inherited enzyme abnormality) or acquired (due to failure of a metabolically important organ) disorder resulting from an abnormal metabolic process. "Excessive signaling (via IL-1R1/IL-1R3) drives pathology in auto-inflammatory, autoimmune, and metabolic diseases." (PMID 41415279, 2025). "In metabolic disorders, IL-1β (produced in response to forms of metabolic stress like high glucose levels) acts on pancreatic β-cells via IL-1R1 to impair function and induce apoptosis." (PMID 41415279, 2025).
brain disorder (1 paper, 2020). A disease affecting the brain or part of the brain. "Because of the wide array of functions that IL1R1 is responsible for in different types of brain cells, further elucidation is required regarding the involvement and role of IL1R1 in the pathogenesis of brain disorders and their corresponding animal models." (PMID 32531902, 2020).
CNS tumors (1 paper, 2018). "Utilizing R2 software for selected GEO databases of different CNS tumors, as mentioned in methodology, we found that high expression levels of IL1R1 were unique to EPNs (p<0.001)." (PMID 30464804, 2018). "IL1R1 expression was fairly specific to EPNs among various CNS tumors analyzed." (PMID 30464804, 2018).
colon (1 paper, 2019). "This agrees with previous studies which have shown IL-1 and TNFα stimulate mucin secretion via IL-1R1 on the basolateral surface of cultured HT29-C1.6E cells and via NF-KappaB pathway in HM3 colon cancer cells." (PMID 30755679, 2019).
head and neck tumors (1 paper, 2024). "In this study, it was found that IL-1α, IL-1β, IL1R1, IL1RL1, IL1F10, IL33, CASP1, and AIM2 were highly expressed in head and neck tumors, while IL1RN, IL1RAPL1, IL1RAPL2, IL18BP, IL18R1, and IL18RAP were low in expressed, which is consistent with previous literature." (PMID 39461030, 2024).
peripheral neuropathy (1 paper, 2019). A disorder affecting the peripheral nervous system. "Secondly, blockade of IL-1R1 with intrathecal administration of the IL-1 receptor antagonist (IL-1ra) during the early phase of peripheral neuropathy increased the expression of both astrocyte P450c17 and GFAP in the spinal cord dorsal horn, and this increase was blocked by IL-1β administration." (PMID 31281242, 2019).
IL1R1 also shares sentences with these, for which no sentence is quoted: cryopyrin-associated periodic syndrome (9 papers); type 2 diabetes (8); heart failure (6); immune dysfunction (6); hematological malignancies (5); periodontitis (5); peritonitis (5); atopic dermatitis (4); multiple myeloma (4); skin infection (4); acute cystitis (3); amyotrophic lateral sclerosis (3); aspergillosis (3); bacteremia (3); Cerebral ischemia (3); colon cancer (3); diabetic nephropathy (3); Fever (3); keratoconus (3); liver disease (3); metastatic tumors (3); pancreatic adenocarcinoma (3); Parkinson disease (3); psychiatric disorder (3); ulcer (3); acute myocardial infarction (2); airway hyperresponsiveness (2); Allergy (2); anemia (2); Arrhythmia (2).
A further 180 diseases each share a sentence with IL1R1 in 2 papers or fewer.